LINC00578 (long independently transcribed non-coding RNA 578)
Synonyms: AC026355.2
Gene: Long non-coding RNA gene on chromosome 3 (177,377,207 to 177,767,379, forward strand). Ensembl gene ENSG00000228221.
Gene Ontology:
Biological process: SRP-dependent cotranslational protein targeting to membrane, signal sequence recognition
Cellular component: signal recognition particle, endoplasmic reticulum targeting
Diseases named in the same sentence as LINC00578 in open-access papers:
LINC00578 is named in the same sentence as 12 diseases in open-access papers, as found by Europe PMC text mining. Sharing a sentence is not in itself a finding about the gene and the disease. The quoted sentences say what the papers report.
pancreatic cancer (6 papers, 2020 to 2025). "It has been reported that LINC00578 is associated with OS in pancreatic cancer and lung adenocarcinoma." (PMID 33216456, 2021). "It has been reported that LINC00578 is associated with worse OS in pancreatic cancer and lung adenocarcinoma." (PMID 32867770, 2020). "We hypothesized that LINC00578 is associated with ferroptosis in pancreatic cancer." (PMID 36846713, 2023). "The findings suggest that LINC00578 mediates the inhibition of ferroptosis in pancreatic cancer by specifically interacting with UBE2K, thereby impeding the ubiquitination process of SLC7A11, and consequently fostering the progression of pancreatic cancer." (PMID 39827195, 2025). "Then, we wondered how LINC00578 promotes SLC7A11 expression to inhibit ferroptosis in pancreatic cancer." (PMID 36846713, 2023). "This study illustrates that LINC00578 promotes pancreatic cancer cell progression and suppresses ferroptosis by directly binding UBE2K to inhibit the ubiquitination of SLC7A11." (PMID 36846713, 2023). "In this study, we discovered that LINC00578 acted as a regulator of ferroptosis in pancreatic cancer." (PMID 36846713, 2023). "LINC00578 positively regulated cell proliferation and invasion in vitro and tumorigenesis in vivo in pancreatic cancer." (PMID 36846713, 2023). "LINC00578 was found as a potential biomarker in lung adenocarcinoma, major depressive disorder, and pancreatic cancer." (PMID 33225954, 2020). "Importantly, we first demonstrated that LINC00578 overexpression can inhibit ferroptosis by targeting SLC7A11 in pancreatic cancer, suggesting that LINC00578 regulates pancreatic cancer progression by inhibiting SLC7A11-dependent ferroptosis." (PMID 36846713, 2023). "This study elucidated that LINC00578 acts as an oncogene to promote pancreatic cancer cell progression and suppress ferroptosis by directly combining with UBE2K to inhibit the ubiquitination of SLC7A11, which provides a promising option for the diagnosis and treatment of pancreatic cancer." (PMID 36846713, 2023). "Subsequently, the expression of LINC00578 in the Su cohort of 50 paired cases was examined to validate the increased level of LINC00578 in pancreatic cancer, and the results showed that the expression level of LINC00578 was significantly higher in pancreatic cancer tissues than in benign tissues." (PMID 36846713, 2023). "In addition, LINC00578 was found to be related to the advanced clinical stage in pancreatic cancer patients." (PMID 36846713, 2023). "In addition, another study indicated that LINC00578 is upregulated and could be a prognostic signature in pancreatic cancer." (PMID 36846713, 2023). "Therefore, we focused on investigating the role of LINC00578 in pancreatic cancer." (PMID 36846713, 2023). "Therefore, LINC00578 plays a positive regulatory role in pancreatic cancer progression." (PMID 36846713, 2023). "However, it is elusive whether LINC00578 participates in pancreatic cancer progression through SLC7A11-independent ferroptosis." (PMID 36846713, 2023). "To identify the biological role of LINC00578 in pancreatic cancer, we first upregulated the expression of LINC00578 in the PATU8988 cell line and downregulated the expression of LINC00578 in the PL45 cell line using lentivirus stable transfection." (PMID 36846713, 2023). "Therefore, we deduced that LINC00578 impeded the ubiquitination of SLC7A11, which inhibits ferroptosis in pancreatic cancer." (PMID 36846713, 2023).
breast carcinoma (2 papers, 2021). "In accordance with our results, LINC01016 was low‐risk autophagy‐related lncRNA and LINC00578 was high‐risk autophagy‐related lncRNA, both with prognostic value in breast cancer patients." (PMID 33216456, 2021). "In conclusion, we identified a novel autophagy‐related prognostic risk model consisting of 11 lncRNAs (U62317.4, LINC01016, LINC02166, C6orf99, LINC00992, BAIAP2‐DT, AC245297.3, AC090912.1, Z68871.1, LINC00578 and LINC01871) in breast cancer." (PMID 33216456, 2021). "The predicting value of 11 sARLNRs (U62317.4, LINC01016, LINC02166, C6orf99, LINC00992, BAIAP2-DT, AC245297.3, AC090912.1, Z68871.1, LINC00578, and LINC01871) was also identified in breast cancer." (PMID 34414116, 2021).
mesothelioma (1 paper, 2022). A usually malignant and aggressive neoplasm of the mesothelium which is often associated with exposure to asbestos.
LINC00578 also shares sentences with these, for which no sentence is quoted: cancer (3 papers); lung adenocarcinoma (3); tumor (2); colon adenocarcinoma (1); esophageal carcinoma (1); hepatitis B (1); lung carcinoma (1); major depressive disorder (1); pancreatic adenocarcinoma (1).